ALB (albumin)
Diseases named in the same sentence as ALB in open-access papers (continued):
Sharing a sentence is not in itself a finding about the gene and the disease.
Cachexia (continued). "All of the following parameters reflecting the nutritional status of CHF patients—body weight, BMI, FM, FFM and albumin—were significantly reduced in the cachexia group (p < 0.05)." (PMID 32260434, 2020). "Although serum albumin, one of the representative markers for systemic inflammation, was used to define cachexia risk in this study, the absence of a biomarker that better reflects the muscle wasting process may weaken the relevance of our risk model for cancer cachexia." (PMID 32423395, 2020). "In contrast, BMI, plasma concentrations of hemoglobin, lymphocyte count, total protein, albumin, prealbumin, total cholesterol and ApoE of patients in the cancer cachexia group were significantly lower than in non-cachexia group." (PMID 31788012, 2019). "C-reactive protein >10 mg/L and coinciding s-albumin <30 g/L was referred to as “laboratory cachexia”." (PMID 29534089, 2018). "Underlining this, our dropped out patients presented significantly higher CRP values and leucocyte counts, less serum albumin, total protein and low hemoglobin concentrations, indicating a higher inflammatory burden, disease severity and advanced cachexia." (PMID 30208857, 2018). "One component in each of the 4 categories for the wasting syndrome was retained: serum albumin ≤ 38 g/L, BMI ≤ 23 Kg/m2, serum creatinine ≤ 818 μmol/L, and normalized protein catabolic rate (nPCR) ≤ 0.8 g/kg/day." (PMID 29075534, 2017). "Despite the consensus recommendation of albumin levels being around 3.2 g/dL, for cachexia diagnosis, CC showed a variation from 2.79 to 4.58 g/dL." (PMID 28288584, 2017). "Serum albumin and serum protein were significantly decreased (p < 0.001) in cancer patients with cachexia." (PMID 28193264, 2017). "C-reactive protein, albumin, hemoglobin, and IL-6, biochemical markers of cachexia, were also evaluated." (PMID 26732354, 2015). "Decreased albumin concentrations are involved with cachexia and are common laboratory features in malignant diseases." (PMID 23761834, 2013). "Another study in Israel found that cachexia and lower albumin levels were related to mortality on multivariate analysis." (PMID 20811589, 2011). "CRP (P<0.0001), albumin (P<0.0001) and haemoglobin (P<0.0001) were also significantly different among the cachexia groups." (PMID 21934689, 2011). "As these variables can be calculated from routinely collected clinical data points—patient weight, height, ANC, ALC and albumin—these findings may be useful for clinical prognostication and decision making around cachexia interventions." (PMID 39817619, 2025). "Thus, the present study specifically set optimal cutoff values of albumin, prealbumin and transferrin for cancer cachexia population determined by standardized log-rank statistics, with figures of 38.7, 0.17, and 2.29 g/L respectively." (PMID 38438901, 2024). "Furthermore, we have observed that NLR‐ and ALB‐based cachexia remains an effective tool in predicting adverse outcomes in patients with cancer." (PMID 39192568, 2024). "Cancer cachexia is a multifactorial syndrome causing progressive skeletal muscle loss leading to progressive functional deterioration and is associated with increased production of CRP, reduced albumin, and a worse performance status (lower AKPS)." (PMID 39628313, 2024). "Logistic regression analysis also identifies albumin as an independent factor of cachexia." (PMID 39272892, 2024). "These two studies suggest that when albumin is used as a biomarker in trials in which the inflammatory genesis of cachexia is targeted via an anti‐inflammatory intervention, it may prove valuable as an endpoint." (PMID 38783477, 2024). "The researchers postulate that the observed decrease in albumin level was due to a dilution effect rather than a massive loss or cachexia." (PMID 38396869, 2024). "Albumin is currently viewed as a marker of cachexia, and there is a lack of data that may explain its role in contributing to the process of cachexia." (PMID 38022578, 2023).
Cachexia (continued). "The wasting syndrome, also known as cachexia, in CKD patients is characterized by symptoms such as reduced appetite, heightened energy expenditure, diminished protein reserves evidenced by low serum albumin levels, and both weight and muscle mass loss." (PMID 38276262, 2023). "Of note, the decrease in albumin preceded the development of cachexia." (PMID 38022578, 2023). "Additionally, serum albumin was particularly noteworthy as an indicator for frailty and cachexia in patients with TR." (PMID 35845070, 2022). "The median serum albumin level in this group was low 1.99 g/dl (IQR 1.8–2.03) likely as a reflection of cachexia and other factors and may explain the low SAAG findings." (PMID 36064324, 2022). "Hemoglobin, albumin, and platelet count were used as blood‐based markers of cachexia." (PMID 34791809, 2022). "A study showed that carfilzomib in combination with z-VAD-fmk in a mouse model of cancer-induced cachexia reduced muscle wasting, tumor burden, modulated metabolism, increased glucose, albumin, and total proteins levels and lowered triglyceride fatty acids levels." (PMID 34832866, 2021). "However, using albumin levels and lymphocyte counts, the components used for PNI calculation, cancer cachexia associated with growth factors release, impaired cell-mediated immune response, and angiogenesis can be estimated." (PMID 33482792, 2021). "ALB levels reflecting the nutritional status of patients could better identify potential cachexia patients." (PMID 34414685, 2021). "This may be explained as the present study included only CD patients, who often suffer from low albumin levels and cachexia, and 17.2% of our patients had a BMI under 18.5 kg/m2." (PMID 34142229, 2021). "One component in each of the 4 categories for the wasting syndrome (according to the ISRNM nomenclature) was retained: serum albumin <38 g/L, BMI < 23 kg/m2, serum creatinine < 818 μmol/L (for this sample of Afro-Carribean HD patients), and nPCR < 0.8 g/kg/day." (PMID 32206350, 2020). "Similarly, the multivariate analysis model indicates that albumin and Cm emerge as the independent factors related to cachexia incidence in CHF women (OR = 50.48 and OR = 34.49, respectively)." (PMID 32260434, 2020). "The serum albumin content was significantly lower in CC, when compared to N, however, the detected concentrations (4.03 [3.47; 4.59] g/dl) were superior to those published by the international consensus for the diagnosis of cachexia." (PMID 32083092, 2020). "Several components of the cachexia definition were also present in patients with other syndromes, e.g. anorexia and low hemoglobin levels in frail patients and reduced body mass, fat-free mass and albumin levels in malnourished patients." (PMID 31029082, 2019). "Therefore, many scholars chose prealbumin as a more sensitive marker to predict prognosis than albumin during cachexia progression." (PMID 31889993, 2019). "Albumin accumulation in the extravascular space is a common characteristic of many pathological conditions, like cancer, infections, and immune disorders, and many of these diseases are characterized by cachexia." (PMID 31195727, 2019). "When male cancer cachexia and male non-cachexia patients were compared, IL-6 and platelet were significantly elevated in the cachexia group, whereas total protein, albumin, prealbumin, ApoE, lymphocyte counts and hemoglobin were significantly reduced in the cachexia group." (PMID 31788012, 2019). "Also, Zn2+ and Ca2+ homeostasis can be affected by reduced plasma albumin levels due to cachexia (number 16)." (PMID 28417928, 2017). "The dietary habits in hemodialysis patients were examined in the DOPPS and other studies, and documented associations of all-cause mortality and various nutrient indices (serum creatinine, serum albumin, normalized protein catabolic rate, body mass index, and cachexia) and also with anorexia." (PMID 28264035, 2017).
Cachexia (continued). "Due to the presence of cachexia caused by SIR-induced hypercytokinemia, patients in group B were expected to exhibit fewer clinical characteristics on the basis of nutritional status, neutrophil/lymphocyte ratio, and serum ALB level than those in group A." (PMID 27151090, 2016). "In essence, a low BMI could be accompanied by low albumin and hemoglobin levels and this could become obvious in cancer patients because of the energy disturbance resulting from cachexia." (PMID 27418926, 2016). "In the blood samples, WBC counts were higher in the cachexia group (11,722 vs. 5,873/μL), as were CRP content (7.1 vs. 2.5 mg/dL), and serum IL-6 levels (40.2 vs. 13.0 pg/mL); however, the cachexia group’s albumin levels were lower (2.7 vs. 3.5 g/dL) than in the non-cachexia group." (PMID 25010770, 2014). "Finally, we examined the proposed cut-off values of CRP, hemoglobin and albumin for diagnosis of cachexia, in order to establish their clinical usefulness." (PMID 23294910, 2013). "Midkine was related to inflammation and was correlated with albumin concentration, while the associations were not affected by cachexia." (PMID 20920199, 2010). "Furthermore, the literature provides convincing evidence that markers of cachexia, including poor appetite, involuntary weight loss, in particular lean muscle, increased REE and decreased albumin are commonly observed in patients recovering from PFF." (PMID 20964865, 2010). "We found 71 proteins that correlated with cachexia severity via weight loss grade, weight loss, skeletal muscle index and radiodensity (r ≥ |0.50|, p ≤ 0.05), including some known cachexia mediators/markers (LEP, MSTN, ALB) as well as novel proteins (e.g., LYVE1, C7, F2)." (PMID 33334063, 2020). "Usually, diagnostic tools for cachexia include loss of weight and lean body mass, fatigue, anorexia, reduced physical performance (for example, total activity or 6-min walk distance) and biochemical abnormalities of c-reactive protein (CRP), albumin, and protein." (PMID 28193264, 2017). "The authors propose an objectively measured laboratory cachexia score (LCAS) which combines systemic inflammation as measured by the widely validated mGPS (a CRP and albumin-based score) and metabolic dysfunction as measured by LDH." (PMID 40133911, 2025). "By integrating Cr and CAR (CRP/albumin) through a random forest model, the CCAR index simultaneously captures three key pathological dimensions of cachexia: inflammation, nutrition and metabolism." (PMID 41216846, 2025). "The Fearon consensus criteria for cachexia, WLGS, NLR, albumin and PNI were readily determined using routine clinical measurements and lab tests—weight, height, ANC, ALC and albumin collected as part of vitals, blood count and metabolic panels." (PMID 39817619, 2025). "Tocilizumab demonstrated significant benefits in survival and various clinical parameters, including body weight, albumin, CRP, mGPS and symptom burden in patients with NSCLC and concurrent IL‐6‐elevated cachexia." (PMID 39523982, 2024). "Albumin, NLR, Hb, PLR, SII, TNFα, IL-8, and CRP were reliable indicators of QoL, appetite, and cachexia." (PMID 38744744, 2024). "We constructed an inflammatory biomarker‐based cachexia model using well‐established systemic inflammatory markers, such as CRP, NLR, ALB and GPS, based on previous studies, and compared their diagnostic performance." (PMID 39192568, 2024). "ROC curve analysis suggested that a combination of choline and Trp predicts cachexia more successfully than CRP and albumin." (PMID 37803016, 2023). "Albumin and CRP concentration have been predictive of patient outcomes and serve as examples of APP that have clinical applicability to cachexia." (PMID 38022578, 2023). "In this study of 324 GC patients, we calculated the CXI with SMI, serum albumin, and NLR: three cachexia-related parameters." (PMID 36139560, 2022).
Cachexia (continued). "Furthermore, previous studies demonstrated that NLR and serum albumin had significant associations with the prognosis in patients with GC, which might account for why low CXI, instead of cachexia diagnosed by Fearon’s criteria, was significantly associated with worse OS in this study." (PMID 36139560, 2022). "Cachexia index (CXI), a new measure of cachexia, is consisted of three objective indicators including SMI, serum albumin, and neutrophil-lymphocyte ratio (NLR)." (PMID 36212479, 2022). "The three cachexia groups that were defined had also gradually higher CRP, lower albumin and lower haemoglobin levels." (PMID 21934689, 2011). "Therefore, we further explored the predictive power of various inflammatory markers in cachexia patients and found that the CRP‐to‐albumin ratio (CAR) performed the best among these composite indices." (PMID 41216846, 2025). "Additionally, a higher percentage of patients with cachexia had NRS 2002 scores of 3 or higher (70.3% vs. 18.6%), ECOG grades above 1 (63.7% vs. 52.1%), had lower values of BMI, CC, HGS, albumin, WBC and lymphocyte count and showed higher values in NLR." (PMID 40504106, 2025). "The cachexia predictors—the Fearon consensus criteria for cachexia, WLGS, NLR, albumin and PNI—demonstrated clear negative association with overall survival as well as the functional outcomes of disability‐free and hospitalization‐free survival." (PMID 39817619, 2025). "Although no variation in serum albumin was seen between cachexia severities, the distribution was lower in both groups compared to control (p < 0.001, ω2 = 0.091)." (PMID 38966634, 2024). "The levels of serum proteins and albumin significantly differ between cancer patients with cachexia and those without cachexia." (PMID 37523113, 2024). "In addition, both factors were associated with levels of different cytokines, namely CRP with interleukin-1β, a driver of MF pathogenesis, and albumin with TNF-α, a key mediator of cachexia." (PMID 36900271, 2023). "The use of fish oil may benefit patients with GI cancers who are either pre-cachectic or developed cancer cachexia and abnormal CPR or albumin levels (mGPS 1 or 2), at least regarding weight maintenance with minimal potential side effects." (PMID 37571328, 2023). "Compared to non-cachectic patients, patients with cachexia had lower baseline weight and plasma albumin before PD-1/PD-L1 blockade treatment (p = 0.039, p = 0.013, respectively)." (PMID 36831513, 2023). "Although hemoglobin and albumin are reportedly lower in subjects with cachexia, we did not observe any differences in our cohort between subjects with cachexia and those without." (PMID 35269531, 2022). "When comparing FA abundance with albumin, lauric and vaccenic acids were strongly negatively correlated with albumin in subjects without cachexia (r = –0.533, p = 0.006 and r = –0.560, p = 0.004; respectively)." (PMID 35269531, 2022). "For the diagnosis of cachexia, we used serum hemoglobin, CRP, and albumin." (PMID 34630405, 2021). "Nevertheless, its predictive value, in combination with other markers such as albumin, CRP, GDF‐15, or IL‐6, for instance, may represent an efficient signature for diagnosis of cachexia." (PMID 34427055, 2021). "In this study, we first compared the differences in clinical data between cancer cachexia and non-cachexia patients, regardless of gender; albumin, prealbumin, lymphocyte count and other conventional nutritional markers decreased in cachexia patients." (PMID 31788012, 2019). "Cachexia progression further increased STAT-3 phosphorylation, though there was no change in liver gp130 and albumin protein content with cachexia progression." (PMID 25789991, 2015). "There is no sign of cachexia in our subjects, as most of them did not lost weight or have decreased serum albumin level." (PMID 25622826, 2015).
Cachexia (continued). "Meanwhile, postoperative NRI may be influenced by surgical stress, fluid shifts, and acute-phase responses, which can transiently alter albumin and weight independent of cancer-related cachexia or baseline reserves." (PMID 40635897, 2025). "In addition to low albumin and high CRP, low AKPS is a plausible additional surrogate of cachexia, and this relationship to noroxycodone could also be studied in future." (PMID 39628313, 2024). "Similarly, the serum concentration of LCN2 in lung cancer patients with cachexia was higher than those without cachexia and was negatively related to BMI and serum albumin levels in these patients." (PMID 38035773, 2024). "Cancer cachexia patients were more likely to be male, older, have a history of smoking and drinking, have advanced tumor stage, ECOG grade > 1, lower BMI, calf circumference and hand grip strength, increased NLR, and decreased albumin, prealbumin, and transferrin levels." (PMID 38438901, 2024). "Regarding biochemistry and haematology, patients with cachexia hadsignificantly increased c-reactive protein levels (average of 30.7 vs 15.3 mg/Lin the not cachectic group), and significantly decreased albumin (37.9 vs 40.2)and red blood cell count (3.8 vs 4.2)." (PMID 35729767, 2022). "Although hemoglobin and albumin were not significantly lower in patients with cachexia, we still assessed whether any FAs correlated with either clinical value." (PMID 35269531, 2022). "Serum irisin level was significantly higher in the cachexia group than in the controls (Irisin (μg/mL); 2.6 (IQR:2.2–4.4) vs. 2.1 (IQR:1.8–2.4); p = 0.001), and positively correlated with BNP levels and NYHA class, and negatively correlated with BMI and serum albumin level (all p values: <0.001)." (PMID 32260434, 2020). "There was a small decrease in albumin over the same period of time in both groups, with a median change of − 0.30 g/dL in patients with follow-up cachexia and − 0.55 g/dL in patients without follow-up cachexia." (PMID 32103356, 2020). "Blood tests showed significant differences in protein levels (P = 0.037) and albumin levels (P < 0.001), with significantly lower levels in patients with cachexia compared to patients without cachexia, demonstrating a worse nutritional status in cachectic patients." (PMID 19635171, 2009). "Additionally, serum albumin concentration was significantly lower in HIV-infected subjects who suffered wasting syndrome than the HIV-positive individuals without wasting (2.1 g/dL versus 2.7 g/dL; P = 0.01)." (PMID 19068104, 2008). "Additionally, γ-linolenic acid was positively correlated with albumin in subjects without cachexia." (PMID 35269531, 2022). "A limitation of this study was the absence of serum albumin in the candidate variables, although it has been shown to be an important prognostic marker in older age in community-living subjects, in hospitalized older patients and in other cachexia-inducing diseases." (PMID 26859298, 2016). "None of the cachexia variables were significant predictors of disability rate, and neither NLR nor albumin was a significant predictor of admission rate." (PMID 39817619, 2025). "However, our growing pigs may have experienced sarcopenic changes rather than cachexia or growth inhibition because a previous study showed no pain, diarrhea, or decreased food intake, and similar serum biochemical indices (protein and albumin levels), indicating comparable nutritional status." (PMID 39201422, 2024). "In this group there is still a significant difference between cachexia and non-cachexia regarding AP (p < 0.001), CHE (p < 0.001), Quick (p < 0.05) and serum albumin (p < 0.001) but not in case of GGT (p = 0.154)." (PMID 28193264, 2017). "Several clinical studies have reported that the increase of C-reactive protein (CRP), a liver-derived positive acute phase protein (APP), and a decrease of albumin, a negative APP, correlates with severity of cachexia and negatively with prognoses of cancer patients." (PMID 37803016, 2023).